IGHV3-7 (immunoglobulin heavy variable 3-7)
Description:
V region of the variable domain of immunoglobulin heavy chains that participates in the antigen recognition. Immunoglobulins, also known as antibodies, are membrane-bound or secreted glycoproteins produced by B lymphocytes. In the recognition phase of humoral immunity, the membrane-bound immunoglobulins serve as receptors which, upon binding of a specific antigen, trigger the clonal expansion and differentiation of B lymphocytes into immunoglobulins-secreting plasma cells. Secreted immunoglobulins mediate the effector phase of humoral immunity, which results in the elimination of bound antigens. The antigen binding site is formed by the variable domain of one heavy chain, together with that of its associated light chain. Thus, each immunoglobulin has two antigen binding sites with remarkable affinity for a particular antigen. The variable domains are assembled by a process called V-(D)-J rearrangement and can then be subjected to somatic hypermutations which, after exposure to antigen and selection, allow affinity maturation for a particular antigen.
Synonyms: IGHV37; VH
Tractability: Antibody: its Gene Ontology location is reachable by antibodies, with high confidence; UniProt places it where antibodies can reach, with medium confidence; UniProt predicts a signal peptide or a membrane-spanning region.
Gene: Immunoglobulin variable (V) gene on chromosome 14 (106,062,151 to 106,062,683, reverse strand). Ensembl gene ENSG00000211938.
Subcellular location: Secreted; Cell membrane
Pathways (Reactome):
Immune System: Antigen activates B Cell Receptor (BCR) leading to generation of second messengers; CD22 mediated BCR regulation; Classical antibody-mediated complement activation; FCERI mediated Ca+2 mobilization; FCERI mediated MAPK activation; FCERI mediated NF-kB activation; FCGR activation; Fc epsilon receptor (FCERI) signaling; Immunoregulatory interactions between a Lymphoid and a non-Lymphoid cell; Initial triggering of complement; Regulation of Complement cascade; Regulation of actin dynamics for phagocytic cup formation; Role of LAT2/NTAL/LAB on calcium mobilization; Role of phospholipids in phagocytosis
Disease: FCGR3A-mediated IL10 synthesis; FCGR3A-mediated phagocytosis; Potential therapeutics for SARS
Hemostasis: Cell surface interactions at the vascular wall
Vesicle-mediated transport: Scavenging of heme from plasma
Gene Ontology:
Molecular function: antigen binding
Biological process: immune response; immunoglobulin mediated immune response
Cellular component: blood microparticle; extracellular exosome; extracellular region; plasma membrane
Homologues: Paralogues in human: IGHV3-48 (91% identical), IGHV3-21 (89% identical), IGHV3-74 (89% identical), IGHV3-13 (87% identical), IGHV3-33 (87% identical), IGHV3-23 (86% identical), IGHV3-30 (86% identical), IGHV3OR16-13 (85% identical), IGHV3-11 (85% identical), IGHV3-66 (85% identical), IGHV3OR16-10 (85% identical), IGHV3-20 (83% identical), and 65 more.